STX8 (syntaxin 8)
Description:
Vesicle trafficking protein that functions in the early secretory pathway, possibly by mediating retrograde transport from cis-Golgi membranes to the ER.
Synonyms: CARB
Tractability: Antibody: its Gene Ontology location is reachable by antibodies, with high confidence; UniProt predicts a signal peptide or a membrane-spanning region. PROTAC: UniProt records ubiquitination sites on it; ubiquitination databases record sites on it; its protein half-life has been measured.
Gene: Protein-coding gene on chromosome 17 (9,250,471 to 9,576,591, reverse strand). Ensembl gene ENSG00000170310.
Subcellular location: Membrane
Subcellular location (Human Protein Atlas): Vesicles; Cytosol
Gene Ontology:
Molecular function: chloride channel inhibitor activity; protein binding; syntaxin binding; SNARE binding; ubiquitin protein ligase binding
Biological process: early endosome to late endosome transport; regulation of protein localization to plasma membrane
Cellular component: early endosome; endosome; late endosome; perinuclear region of cytoplasm; recycling endosome; trans-Golgi network; vesicle; endoplasmic reticulum; plasma membrane; membrane; phagocytic vesicle
Genetic constraint (gnomAD): Loss-of-function variants: 18 observed, 25.99 expected, observed/expected ratio (o/e) 0.69, 90% interval 0.48 to 1.03. The upper end of that interval is the gene's LOEUF score, 1.03, which puts it in group 4 of 6, group 1 being the genes least tolerant of losing a copy. Missense variants: 282 observed, 255.73 expected, observed/expected ratio (o/e) 1.1, 90% interval 1 to 1.22. Synonymous variants: 107 observed, 94.33 expected, observed/expected ratio (o/e) 1.13, 90% interval 0.97 to 1.33.
Homologues: Orthologues: chimpanzee STX8 (100% identical), guinea pig STX8 (95% identical), mouse Stx8 (93% identical), rat Stx8 (93% identical), dog STX8 (92% identical), macaque STX8 (88% identical), pig STX8 (84% identical), tropical clawed frog stx8 (61% identical), zebrafish stx8 (57% identical), rabbit STX8 (50% identical), Drosophila melanogaster Syx6 (22% identical), Caenorhabditis elegans syx-6 (13% identical). Paralogues in human: STX6 (23% identical), STX10 (22% identical).
Diseases named in the same sentence as STX8 in open-access papers:
STX8 is named in the same sentence as 15 diseases in open-access papers, as found by Europe PMC text mining. Sharing a sentence is not in itself a finding about the gene and the disease. The quoted sentences say what the papers report.
skin cancer (4 papers, 2012 to 2024). "PTGES2, RNASET2, SF3B4, and STX8 showed significant associations with skin cancer after FDR correction." (PMID 39035989, 2024). "Phenotype scanning revealed that STX8 was associated with skin cancer due to its influence on congenital skin malformations." (PMID 39003418, 2024). "STX8 has been associated with congenital skin malformations which may account for its link with skin cancer." (PMID 39003418, 2024). "Furthermore, prostaglandin E synthase 2 (PTGES2), ribonuclease T2 (RNASET2), SF3B4, and STX8 were significantly associated with skin cancer risk after FDR correction for multiple testing (FDR <0.05)." (PMID 39035989, 2024). "Interestingly, PTGES2, RNASET2, SF3B4, and STX8, associated with skin cancer risk, were also significantly associated with NMSC and BCC risks." (PMID 39035989, 2024). "Per standard deviation increase in genetically predicted levels of protein, the OR of skin cancer ranged from 0.44 (95% CI = 0.28–0.69) for splicing factor 3B subunit 4 (SF3B4) to 1.50 (95% CI = 1.18–1.91) for Syntaxin-8 (STX8)." (PMID 39035989, 2024). "ASIP was colocalized with all three types of skin cancer and STX8, KRT5, GSK3A, CTSS, and TNFSF8 with BCC." (PMID 39003418, 2024).
asthma (1 paper, 2022). "Gene expression commonly regulated in PTSD and severe asthma, included ORMDL3 a gene known to be associated with asthma risk and STX8, which is involved in TrkA signaling." (PMID 36206293, 2022). "Upregulated in the blood of severe asthma and PTSD subjects were mRNA encoding Syntaxin 8 (STX8), and Rho GTPase Activating Protein 24 (ARHGAP24)." (PMID 36206293, 2022).
autoimmune disease (1 paper, 2025). A disorder resulting from loss of function or tissue destruction of an organ or multiple organs, arising from humoral or cellular immune responses of the individual to their own tissue constituents. "STX8 and YES1 are implicated in T-cell activation, MAP4K5, RRM2B, FOXO1, ERBB2IP and INPPL1 can promote inflammation and KIM1, MVK and BANK1 have been associated with autoimmune diseases." (PMID 40247373, 2025).
glioblastoma (1 paper, 2010). The most malignant astrocytic tumor (WHO grade IV). "In a recent study, overexpression of ERRFI1 was shown to decrease proliferation in glioblastoma cells, binding EGFR with STX8, and driving internalized EGFR to late endosomes for degradation, whereas knockdown of ERRFI1 expression resulted in increased tumor invasion." (PMID 21113414, 2010).
Insulin resistance (1 paper, 2016). Increased resistance towards insulin, that is, diminished effectiveness of insulin in reducing blood glucose levels. "In obese patients with T2D, the expression of syntaxin 8 in visceral adipose tissue appeared to be increased, which may result in a decreased level of GLUT4 causing insulin resistance." (PMID 26891264, 2016).
type 2 diabetes (1 paper, 2020). "Elevated exclusively in palmitate vesicles is syntaxin-8 whose expression was described previously as increased in VAT of obese patients with type 2 diabetes and related to markers of IR and inflammation." (PMID 32214011, 2020).
tumor (4 papers, 2010 to 2022). "ERRFI1 overexpression has been shown to reduce proliferation in GBM cells by binding EGFR to Syntaxin-8 and targeting internalized EGFR to late endosomes for degradation, while knockdown of ERRFI1 expression resulted in increased tumor invasion." (PMID 36231068, 2022).
STX8 also shares sentences with these, for which no sentence is quoted: COVID-19 (2 papers); infection (2); gestational diabetes mellitus (1); osteomyelitis (1); pneumonia (1); preeclampsia (1); tracheobronchitis (1); urinary tract infection (1).